KCNQ1OT1 (KCNQ1 opposite strand/antisense transcript 1)
Diseases named in the same sentence as KCNQ1OT1 in open-access papers (continued):
Sharing a sentence is not in itself a finding about the gene and the disease.
breast carcinoma (15 papers, 2015 to 2025). "And KCNQ1OT1, a lncRNA, is confirmed to be associated with breast cancer in both LncRNADisease and Lnc2cancer databases." (PMID 33980147, 2021). "Individuals with KCNQ1OT1-region hypermethylation (>0.474) had a lower risk of breast cancer." (PMID 35681632, 2022). "In summary, the KCNQ1OT1 region could be a potential biomarker for breast cancer risk assessment." (PMID 35681632, 2022). "We discovered and validated that peripheral blood DNA methylation of KCNQ1, KCNQ1OT1, and PHLDA2 at chromosome 11p15.4-15.5 is associated with breast cancer susceptibility." (PMID 35681632, 2022). "KCNQ1OT1 is found to be remarkably high expression in breast cancer tissues and cells, which promoted tumor growth in vivo by regulatingmiR-145/CCNE2." (PMID 34983363, 2022). "Another lncRNA KCNQ1OT1 is correlated with human breast cancer cell development through inverse regulation of miR-145." (PMID 34497807, 2021). "KCNQ1OT1 had significantly higher expression levels in invasive breast carcinoma and was induced by estrogen in estrogen receptor-alpha expressing breast cancer cells." (PMID 30046354, 2018). "KCNQ1OT1 is induced by estrogen in estrogen receptor-alpha (ERα) expressing breast cancer cells and further mediate CDKN1C repression through epigenetic repression." (PMID 26278472, 2015). "Moreover, KCNQ1OT1 was aberrantly highly expressed in breast cancer (BRCA) tissues and cell lines, and it could deteriorate tumor progression via regulating miR-145/CCNE2 expression." (PMID 31827399, 2019). "Additionally, KCNQ1OT1, which was one of the most upregulated lncRNAs in GA samples of our study, was also defined as an oncogene and it has been reported to have significantly higher expression levels in breast cancer and other types of malignant tumors." (PMID 27992366, 2017). "For example, KCNQ1OT1, MALAT1, XIST, and NEAT1 are experimentally confirmed breast cancer-related lncRNAs, which have been ranked 2nd, 11th, 12th, and 19th in the predicted list based on the model of DCSLDA, respectively." (PMID 30046354, 2018). "For example, XIST, KCNQ1OT1 and NEAT1 are there experimentally confirmed breast cancer related lncRNAs, which have been ranked 1st, 8th, and 12th in the predicted list based on the model of HGLDA, respectively." (PMID 26278472, 2015). "Furthermore, after conducting data mining in silico using public databases, the results of our study pointed to 4 lncRNAs, MIAT, KCNQ1OT1, LOC100270804, and FLJ10038, with good potential as candidate biomarkers for breast cancer." (PMID 34209776, 2021).
tongue cancer (14 papers, 2018 to 2023). A malignant neoplasm affecting the tongue. "For instance, KCNQ1OT1 caused the alternation of tongue cancer proliferation and cisplatin resistance by modulating the miR-211-5p-mediated Ezrin/Fak/Src signaling pathway." (PMID 34335862, 2021). "For example, lncRNA KCNQ1OT1 regulates proliferation and cisplatin resistance in tongue cancer via miR-211-5p mediated Ezrin/Fak/Src signaling." (PMID 37875515, 2023). "LncRNA KCNQ1OT1 has also been related to EMT in tongue cancer tissues and cells, promoting survival rate proliferation, migration, and invasion." (PMID 35978835, 2022). "LncRNA KCNQ1OT1 regulates cisplatin resistance in tongue cancer via miR-211-5p-mediated Ezrin/Fak/Src signaling." (PMID 35311096, 2022). "Zhang et al40 showed that KCNQ1OT1 modulated cisplatin resistance and proliferation through regulating miR‐211‐5p in tongue cancer." (PMID 34378327, 2021). "The lncRNA KCNQ1OT1 acts via miR-211–5p and downstream Ezrin/Fak/Src signaling to promote tumor growth and cisplatin resistance in tongue cancer." (PMID 34868237, 2021). "LncRNA KCNQ1OT1 regulates cisplatin resistance by acting as a ceRNA to modulate the expression of miR-211-5p in tongue cancer." (PMID 30992025, 2019). "The numbers of apoptotic cells were decreased, and more tongue cancer cell were suvived under cisplatin pressure due to the KCNQ1OT1 upregulation." (PMID 29970910, 2018). "According to our clinical evidence, KCNQ1OT1 acts as an independent prognostic factor for tongue cancer patients, and it may be valuable for predicting chemoresistance." (PMID 29970910, 2018). "Moreover, LncRNA KCNQ1OT1 has been proved could regulate tongue cancer cell proliferation and cisplatin resistance via miR-211-5p mediated Ezrin/Fak/Src signaling." (PMID 35443864, 2022). "In a tongue SCC study, the upregulation of the lncRNA KCNQ1 opposite strand/antisense transcript 1 (KCNQ1OT1) demonstrated a strong correlation with the survival rate, proliferation, migration, invasion, and EMT of tongue cancer cells." (PMID 35978835, 2022).
lung adenocarcinoma (13 papers, 2018 to 2022). A carcinoma that arises from the lung and is characterized by the presence of malignant glandular epithelial cells. "KCNQ1OT1 is also associated with chemotherapy resistance and acts as a lung adenocarcinoma oncogene." (PMID 35193115, 2022). "For example, KCNQ1 Opposite Strand/Antisense Transcript 1 (KCNQ1OT1) was closely associated with insensitivity of lung adenocarcinoma, and also knockdown of KCNQ1OT1 depressed the expression level of Multidrug Resistance Protein 1 (MDR1) and the paclitaxel resistance." (PMID 30761271, 2019). "In lung adenocarcinoma, lncRNA KCNQ1OT1 was also reported to upregulated radioresistance via miR-372-3p/ATG5 and ATG12 axis." (PMID 35600868, 2022). "For example, KCNQ1OT1 was highly expressed in lung adenocarcinoma and high expression of KCNQ1OT1 is correlated to malignant behaviors, including large tumor size, higher lymph nodes metastasis rate, and advanced TNM stage." (PMID 34404765, 2021). "Ren reported a similar result that KCNQ1OT1 knockdown in lung adenocarcinoma cells suppressed paclitaxel-induced chemo-resistance and contributed to the inhibition of cell proliferation and invasion." (PMID 29970910, 2018). "The lncRNA KCNQ1OT1 is highly expressed in lung adenocarcinoma cells and the knockdown of lncRNA KCNQ1OT1 significantly decreased the expression of MDR1/ABCB1 in A549 adenocarcinomic human alveolar basal epithelial/human ovary cells derived from metastatic site (PA1) cells." (PMID 32164712, 2020). "Furthermore, the knockdown of KCNQ1OT1 depressed chemoresistance to paclitaxel in lung adenocarcinoma." (PMID 32127798, 2020).
non-small cell lung carcinoma (13 papers, 2019 to 2024). A group of at least three distinct histological types of lung cancer, including non-small cell squamous cell carcinoma, adenocarcinoma, and large cell carcinoma. "KCNQ1 overlapping transcript 1 (KCNQ1OT1) is implicated in the pathogenesis of diverse carcinomas including non-small cell lung cancer (NSCLC), gastric cancer, and ovarian cancer." (PMID 33909822, 2021). "Recently, KCNQ1OT1, as a novel lncRNA, was found to be significantly up-regulated in non-small-cell lung cancer (NSCLC) tissues and cell lines and positively correlated with poor prognosis." (PMID 31827399, 2019). "LncRNA KCNQ1OT1 facilitates the progression of non-small-cell lung carcinoma via modulating miRNA-27b-3p/HSP90AA1 axis." (PMID 31001325, 2019). "A further investigation was undertaken to construct a radiation prediction model for early-stage or locally progressed non-small cell lung cancer (NSCLC) using six genes, including APOBEC3B, GOLM1, FAM117A, KCNQ1OT1, PCDHB2, and USP43." (PMID 38613804, 2024).
Sepsis (13 papers, 2020 to 2025). Sepsis is defined as life-threatening organ dysfunction caused by a dysregulated host response to infection. "Potassium voltage-gated channel subfamily Q member 1 opposite strand/antisense transcript 1 (KCNQ1OT1) was reported to exert effects on sepsis-associated diseases including myocardial injury, acute respiratory distress syndrome and preeclampsia in response of LPS treatment." (PMID 34783627, 2021). "According to previous studies, the role of KCNQ1OT1 is controversial in sepsis-associated diseases." (PMID 34783627, 2021). "Therefore, the present study aimed to explore potential correlations involving lnc‐KCNQ1OT1 and inflammation, multiple organ dysfunction, and mortality risk among sepsis patients." (PMID 34761437, 2021). "Down-regulation of KCNQ1OT1 advances cardiac injury through regulating miR-192-5p/XIAP axis during sepsis." (PMID 40041174, 2025). "In this study, miR-154-3p was sharply up-regulated in the sepsis model as a downstream target of KCNQ1OT1." (PMID 37326687, 2023). "To elucidate the molecular mechanism of lncRNA KCNQ1OT1 in regulating the progression of sepsis, we used starBase to predict its potential targets." (PMID 37326687, 2023). "In the present study, we found that KCNQ1OT1 expression was low in the sepsis model, and overall survival was relatively low." (PMID 37326687, 2023). "Collectively, we confirmed that KCNQ1OT1 acted as a sponge for miR-154-3p in the regulation of sepsis progression." (PMID 37326687, 2023). "We found that lnc‐KCNQ1OT1 levels were lower in sepsis patients (median [interquartile range, IQR]: 0.402 [0.288–0.732]) than in HCs (median [IQR]: 0.990 [0.596–1.462]) (p < 0.001)." (PMID 34761437, 2021). "Overall, KCNQ1OT1 aggravates sepsis-induced AKI by activating p38/NF-κB signaling via miR-212-3p/MAPK1 axis." (PMID 34783627, 2021). "In summary, KCNQ1OT1 aggravates sepsis-induced AKI by activating p38/NF-κB pathway via miR-212-3p/MAPK1 axis." (PMID 34783627, 2021). "In conclusion, KCNQ1OT1 aggravates acute kidney injury by activating p38/NF-κB pathway via miR-212-3p/MAPK1 axis in sepsis." (PMID 34783627, 2021). "Long non‐coding RNA potassium voltage‐gated channel subfamily Q member 1 opposite strand 1 (lnc‐KCNQ1OT1) represses inflammation and multiple organ dysfunction, whereas its clinical value in sepsis is unclear." (PMID 34761437, 2021). "Lnc‐KCNQ1OT1 from peripheral blood mononuclear cells were detected by RT‐qPCR in 116 sepsis patients and 60 healthy controls (HCs)." (PMID 34761437, 2021). "Up-regulation of KCNQ1OT1 ameliorated proliferation and impeded apoptosis in sepsis-induced myocardial injury." (PMID 34956235, 2021). "Lnc‐KCNQ1OT1 serves as a potential biomarker for monitoring disease severity and prognosis in patients with sepsis." (PMID 34761437, 2021). "A recent study by Sun and coworkers revealed that the opposite strand/antisense transcript 1 (KCNQ1OT1) lncRNA inhibits sepsis-induced myocardial injury by regulating the miR192-5p/X-linked inhibitor of apoptosis (XIAP) axis." (PMID 33708127, 2021). "Lnc‐KCNQ1OT1 negatively correlated with multiple organ dysfunction and inflammatory indexes in sepsis patients." (PMID 34761437, 2021). "For instance, lnc‐KCNQ1OT1 relieves sepsis‐induced myocardial injury by regulating cardiomyocyte proliferation and apoptosis by modulating the miR‐192‐5p/XIAP axis." (PMID 34761437, 2021). "To investigate the role of lncRNA-KCNQ1OT1 in sepsis, we overexpressed KCNQ1OT1." (PMID 37326687, 2023). "Importantly, functional research findings indicated that KCNQ1OT1 regulated sepsis progression by targeting miR-154-3p/RNF19A axis." (PMID 37326687, 2023). "It was speculated that exosomal KCNQ1OT1 might play a vital role in the progression of sepsis by targeting the miR-154-3p/RNF19A axis." (PMID 37326687, 2023). "Lnc‐KCNQ1OT1 decreased in patients with sepsis than in HCs (p < 0.001)." (PMID 34761437, 2021).
Sepsis (continued). "Moreover, the expression of the KCNQ1OT1 lncRNA is downregulated in rats with sepsis-induced myocardial injury, accompanied by an increased expression of miR-192-5p." (PMID 33708127, 2021). "In addition, the role of KCNQ1OT1 and miR-212-3p in sepsis-induced AKI needs to be further explored in the future." (PMID 34783627, 2021). "Surprisingly, we found that lnc‐KCNQ1OT1 abundance was lower in sepsis patients than in HCs." (PMID 34761437, 2021). "In sepsis patients, lnc‐KCNQ1OT1 was negatively correlated with sequential organ failure assessment (SOFA) scores (r = −0.344, p < 0.001) and several SOFA subscale scores (including respiratory system, coagulation, liver, and renal systems) (all r < 0, p < 0.05)." (PMID 34761437, 2021). "For instance, in myocardial damage mediated by sepsis, the competitive binding of KCNQ1 opposite strand/antisense transcript 1 (KCNQ1OT1) and miR-192-5p modulates the X-linked inhibitor of apoptosis (XIAP) expression, and KCNQ1OT1 overexpression mitigates myocardial injury stemming from sepsis." (PMID 34592882, 2021). "SOFA and APACHE II scores, combined with quantification of lnc‐KCNQ1OT1 expression, could better predict patient prognosis in sepsis cases." (PMID 34761437, 2021). "Considering that sepsis is often correlated with multiple organ dysfunction, we hypothesized that lnc‐KCNQ1OT1 might be correlated with multiple organ dysfunction in sepsis." (PMID 34761437, 2021). "Furthermore, lnc‐KCNQ1OT1 abundance was lower in sepsis deaths (median [IQR]: 0.272 [0.169–0.352]) compared to sepsis survivors (median [IQR]: 0.439 [0.349–0.844]) (p < 0.001)." (PMID 34761437, 2021). "Taken together, lnc‐KCNQ1OT1 levels were negatively correlated with inflammation in sepsis." (PMID 34761437, 2021). "Several studies have shown that lnc‐KCNQ1OT1 is able to inhibit inflammation and multiple organ dysfunction, whereas hyperinflammation and multiple organ dysfunction are hallmarks of sepsis." (PMID 34761437, 2021). "In conclusion, lnc‐KCNQ1OT1 serves as a potential biomarker for monitoring disease severity and prognosis in sepsis patients, which might consequently improve the management of this disease." (PMID 34761437, 2021). "Surprisingly, we discovered that lnc‐KCNQ1OT1 was decreased in sepsis deaths compared to sepsis survivors, and that its expression could discriminate sepsis deaths from sepsis survivors." (PMID 34761437, 2021). "Thus, to explore a more convenient method to predict outcomes in sepsis patients, we evaluated lnc‐KCNQ1OT1 expression in sepsis survivors and sepsis non‐survivors." (PMID 34761437, 2021). "Based on this information, we speculated that lnc‐KCNQ1OT1 levels might be correlated with inflammation and multiple organ dysfunction in sepsis, while the relevant data are obscured." (PMID 34761437, 2021). "In addition, the ROC curve showed that lnc‐KCNQ1OT1 expression had a certain ability to discriminate sepsis deaths from sepsis survivors, with an AUC (95% confidence interval [CI]) of 0.780 (0.678–0.882)." (PMID 34761437, 2021). "However, no relevant research has focused on possible correlations between lnc‐KCNQ1OT1 and inflammation in sepsis." (PMID 34761437, 2021). "Hence, we compared lnc‐KCNQ1OT1 expression between patients with sepsis and HCs." (PMID 34761437, 2021). "Furthermore, lnc‐KCNQ1OT1 decreased in sepsis deaths compared to sepsis survivors, whose expression could discriminate sepsis deaths from sepsis survivors." (PMID 34761437, 2021). "Additionally, lnc‐KCNQ1OT1 levels were lower in sepsis deaths than in sepsis survivors (p < 0.001), and the receiver operating characteristic curve showed that lnc‐KCNQ1OT1 had an acceptable ability to predict 28‐day mortality (area under the curve: 0.780, 95% confidence interval: 0.678–0.882)." (PMID 34761437, 2021). "Thus, we speculated that lnc‐KCNQ1OT1 levels might be dysregulated in sepsis, although related information is scarce." (PMID 34761437, 2021).
Sepsis (continued). "Thus, lnc‐KCNQ1OT1 expression was decreased in patients with sepsis." (PMID 34761437, 2021). "Our study demonstrates that the exosomal KCNQ1OT1 suppresses sepsis via mediating miR-154-3p/RNF19A, which provides a latent target for sepsis treatment." (PMID 37326687, 2023). "For example, lnc‐KCNQ1OT1 negatively regulates inflammatory factors (including TNF‐α, IL‐1β, and IL‐6) in sepsis‐induced myocardial injury and intimal hyperplasia." (PMID 34761437, 2021). "In conclusion, KCNQ1OT1 competes with MAPK1 for the opportunity of interacting with miR-212-3p and release MAPK1 to activate p38/NF-κB signaling, thus aggravating sepsis-induced AKI." (PMID 34783627, 2021). "KCNQ1OT1, the lncRNA having putative RNA–RNA interaction with TLR2, was found to attenuate sepsis-induced myocardial injury via regulating miR-192-5p/XIAP axis." (PMID 33224264, 2020). "To further explore the interaction relationship between KCNQ1OT1, miR-154-3p, and RNF19A in the progression of sepsis, we transfected HUVEC cells with sh-KCNQ1OT1 + NC-inhibitor or sh-KCNQ1OT1 + miR-154-3p inhibitor or sh-KCNQ1OT1 + miR-154-3p inhibitor + sh-RNF19A." (PMID 37326687, 2023). "Thus, we assessed SOFA scores and subscales in sepsis patients, which revealed that lnc‐KCNQ1OT1 was negatively correlated with SOFA scores and its partial subscales (respiratory system, coagulation, liver, and renal systems) in sepsis patients." (PMID 34761437, 2021). "However, the biological function of KCNQ1OT1 in sepsis had not been fully explored, and its exact molecular mechanism needed to be further elucidated." (PMID 37326687, 2023). "Therefore, a negative association was found between lnc‐KCNQ1OT1 levels and SOFA scores and its partial subscales, suggesting that lnc‐KCNQ1OT1 was negatively correlated to multiple organ dysfunction in sepsis." (PMID 34761437, 2021). "However, the mechanism of KCNQ1OT1 in sepsis had not been fully elucidated." (PMID 37326687, 2023). "A potential explanation might be that reduced levels of lnc‐KCNQ1OT1 could exacerbate inflammation by regulating the XIAP axis and promoting multiple organ injury by targeting miRNAs (such as miR‐192‐5p and miR‐146a), while inflammation and multiple organ dysfunction often occur in sepsis." (PMID 34761437, 2021).
bladder cancer (12 papers, 2018 to 2024). "The function of lncRNA KCNQ1OT1 in bladder cancer (BC) remains largely unknown." (PMID 31827399, 2019). "In the present study, we enrolled a total of 12 major lncRNAs with important roles in multiple tumors until December 2016, among which Kcnq1ot1 and PTENP1 have not been investigated in bladder cancer." (PMID 30285771, 2018).
diabetes (11 papers, 2009 to 2025). "Moreover, decreased lnc‐KCNQ1OT1 expression was correlated with the occurrence of diabetes (p = 0.019)." (PMID 34761437, 2021). "However, in studies of type 2 diabetes caused by hepatitis C virus infection, it is shown that KCNQ1OT1 was found to promote the scorch death of β-cells infected by hepatitis C virus through the miR-223-3p/NLRP3 axis, thereby affecting insulin production and accelerating the onset of diabetes and." (PMID 41334450, 2025).